PPWD1 (peptidylprolyl isomerase domain and WD repeat containing 1)
Description:
PPIase that catalyzes the cis-trans isomerization of proline imidic peptide bonds in oligopeptides and may therefore assist protein folding. May be involved in pre-mRNA splicing.
Synonyms: KIAA0073
Tractability: Small molecule: a structure with a bound ligand is known. PROTAC: ubiquitination databases record sites on it; its protein half-life has been measured.
Gene: Protein-coding gene on chromosome 5 (65,563,236 to 65,587,549, forward strand). Ensembl gene ENSG00000113593.
Subcellular location: Nucleus
Subcellular location (Human Protein Atlas): Nuclear bodies
Pathways (Reactome):
Metabolism of RNA: mRNA Splicing - Major Pathway
Gene Ontology:
Molecular function: peptidyl-prolyl cis-trans isomerase activity
Biological process: mRNA splicing, via spliceosome
Cellular component: catalytic step 2 spliceosome; nuclear body; spliceosomal complex; U2-type catalytic step 1 spliceosome; nucleoplasm; nucleus
Genetic constraint (gnomAD): Loss-of-function variants: 43 observed, 68.4 expected, observed/expected ratio (o/e) 0.63, 90% interval 0.49 to 0.81. The upper end of that interval is the gene's LOEUF score, 0.81, which puts it in group 3 of 6, group 1 being the genes least tolerant of losing a copy. Missense variants: 668 observed, 837.9 expected, observed/expected ratio (o/e) 0.8, 90% interval 0.75 to 0.85. Synonymous variants: 230 observed, 270.62 expected, observed/expected ratio (o/e) 0.85, 90% interval 0.76 to 0.95.
Homologues: Orthologues: chimpanzee PPWD1 (99% identical), macaque PPWD1 (99% identical), pig PPWD1 (98% identical), dog PPWD1 (97% identical), mouse Ppwd1 (97% identical), rabbit PPWD1 (97% identical), guinea pig PPWD1 (97% identical), rat Ppwd1 (97% identical), tropical clawed frog ppwd1 (83% identical), zebrafish ppwd1 (81% identical), Drosophila melanogaster CG3511 (58% identical), Caenorhabditis elegans cyn-15 (46% identical). Paralogues in human: PPIL2 (23% identical), PPIE (15% identical), PPIL1 (13% identical), NKTR (13% identical), PPIL3 (13% identical), PPIB (12% identical), PPID (12% identical), PPIG (12% identical), CWC27 (12% identical), PPIC (12% identical), PPIF (11% identical), PPIA (11% identical), and 10 more.
Diseases named in the same sentence as PPWD1 in open-access papers:
PPWD1 is named in the same sentence as 10 diseases in open-access papers, as found by Europe PMC text mining. Sharing a sentence is not in itself a finding about the gene and the disease. The quoted sentences say what the papers report.
osteoporosis (2 papers, 2022 to 2025). A condition of reduced bone mass, with decreased cortical thickness and a decrease in the number and size of the trabeculae of cancellous bone (but normal chemical composition), resulting in increased fracture incidence. "However, LOC111769717 is predicted to be PPWD1, whose expression is associated with post‐menopausal osteoporosis." (PMID 39801206, 2025).
cervical cancer (1 paper, 2020). A primary or metastatic malignant neoplasm involving the cervix. "We found that RP11-284F21.9-miR-769-3p-PPWD1 axis regulated proliferation, migration and invasion of cervical cancer cells both in vitro and in vivo." (PMID 32936290, 2020). "Consistently, the expression of PPWD1 was significantly down-regulated in cervical cancer tissues and cell lines compared with that in control tissues or cell line." (PMID 32936290, 2020). "Taken together, our data indicated that miR-769-3p directly regulated PPWD1 expression and miR-769-3p/PPWD1 axis was critical for proliferation and invasion of cervical cancer cells." (PMID 32936290, 2020). "Here we further extended the understanding of lncRNA–miRNA–mRNA network in cervical cancer by showing that RP11-284F21.9 regulates PPWD1 expressing by competitively binding to miR-769-3p." (PMID 32936290, 2020). "In conclusion, we indicate that RP11-284F21.9 functions as a tumor suppressor in cervical carcinoma via targeting miR-769-3p/PPWD1, providing a potential promising therapeutic target for cervical carcinoma." (PMID 32936290, 2020). "Overall, our data suggest that overexpression of RP11-284F21.9 inhibits tumor growth of cervical carcinoma in vivo via regulating miR-769-3p/PPWD1." (PMID 32936290, 2020). "In addition, Pearson correlation analysis indicated that the expression of miR-769-3p was negatively correlated with the expression of PPWD1 in cervical cancer tissues." (PMID 32936290, 2020). "Taken together, the regulatory network of RP11-284F21.9-miR-769-3p-PPWD1 could be a reliable drug target for cervical cancer therapy." (PMID 32936290, 2020). "In summary, our findings reveal that lncRNA RP11-284F21.9 might be a tumor suppressor in cervical carcinoma and function as a ceRNA in regulating PPWD1 through competitively binding to miR-769-3p." (PMID 32936290, 2020). "The RP11-284F21.9/miR-769-3p/PPWD1 axis could serve as a promising prognostic biomarker and therapeutic target for cervical carcinoma." (PMID 32936290, 2020).
esophageal cancer (1 paper, 2025). A primary or metastatic malignant neoplasm involving the esophagus. "By integrating bioinformatics, experimental validation, and clinical correlation analyses, we identified six SFs (CRNKL1, SNRPB2, RBMX2, DDX46, PPWD1, and CFAP20) that are aberrantly overexpressed in esophageal cancer and tightly linked to poor prognosis." (PMID 40282339, 2025). "Exon 11 skipping of CTTN occurred after knockdown of most survival-related SFs (CRNKL1, SNRPB2, PPWD1, RBMX2, and DDX46), while exon 11 inclusion was observed in esophageal cancer in comparison to normal tissue, both in the TCGA database and in our own full-length sequencing data." (PMID 40282339, 2025).
lung adenocarcinoma (1 paper, 2020). A carcinoma that arises from the lung and is characterized by the presence of malignant glandular epithelial cells. "Promotes EC tumor cell invasion by targeting PPWD1 and increases EC permeability via suppressing CELSR1 in lung adenocarcinoma." (PMID 33363174, 2020).
cancer (5 papers, 2016 to 2025). A tumor composed of atypical neoplastic, often pleomorphic cells that invade other tissues. "CFAP20, PPWD1, and DDX46 were positively correlated with cancer-associated fibroblasts (CAFs)." (PMID 40282339, 2025). "Previous studies have shown that PPWD1 might functional relate to cancer pathogenesis as it has the well-characterized WD40 domain which has critical functions in tumorigenesis." (PMID 32936290, 2020). "We found that CCL15, a chemokine known to promote an immunosuppressive microenvironment and cancer metastasis, was significantly correlated with CRNKL1, SNRPB2, and PPWD1." (PMID 40282339, 2025). "Among 12 genes reported in the literature as SL with RB1 6 genes (PPWD1, SKP2, AURKA, AURKB, E2F1, and E2F3) scored as SL RB1 partners in human cancer patients." (PMID 33591981, 2021).
tumor (4 papers, 2014 to 2021). "We also checked the miR-769-3p and PPWD1 expression in tumor tissues." (PMID 32936290, 2020). "Tumor tissues from pcDNA3.1-RP11-284F21.9 group showed remarkably lower expression levels of miR-769-3p, with significantly higher expression levels of PPWD1." (PMID 32936290, 2020). "Conversely, in normal kidney tissue PPWD1, LUMCH1 and ZNF600 were down regulated in smokers compared to non-smokers; however, these genes were up regulated in smokers versus non-smokers in ccRCC tumor tissue." (PMID 24479813, 2014).
PPWD1 also shares sentences with these, for which no sentence is quoted: breast carcinoma (1 paper); endometrial cancer (1); lung carcinoma (1); melanoma (1).